STAT3 (signal transducer and activator of transcription 3)
Diseases named in the same sentence as STAT3 in open-access papers (continued):
Sharing a sentence is not in itself a finding about the gene and the disease.
cancer (continued). "For JAK2/STAT3 signaling pathway, it was reported to plays vital roles in the EMT, metastasis and drug resistance of various cancers 28-29." (PMID 35813296, 2022). "Previous studies have shown that HNRNP is involved in cancer-related pathways, including protein secretion, mitochondrial spindle, G2/M checkpoint, DNA repair, IL6/JAK/STAT3 signaling, and other pathways." (PMID 36061307, 2022). "STAT3 and CREB are proto-oncogenes often persistently active in cancer, thus making them valuable therapeutic targets." (PMID 35741451, 2022). "Activation of Jak/Stat3 signaling pathway plays a critical role in promoting tumorigenesis, epithelial and mesenchymal transition (EMT), chemo-resistance, and cancer cell stemness." (PMID 35600882, 2022). "In that context, activation of STAT3 has been shown to be critical in regulating EMT and other tumorigenic functions in cancer." (PMID 36585738, 2022). "PRL3 promoted metastasis of cancer cells by regulating a diverse downstream prometastatic effector molecule, via NF-κB pathway, AKT, STAT3, EGFR, IL-8 and CCL26." (PMID 35246503, 2022). "These combinations offer achieving higher radio- and chemo- sensitization through alteration in the key signaling pathways such as AMPK, STAT3, NF-ĸB, Hedgehog, PI3K/Akt/mTOR, Notch, GSK3β, and Wnt related to cancer stemness and drug resistance." (PMID 35740529, 2022). "The STAT3 level is correlated with GBM malignancy, indicating its participation in increasing the migration potential of cancer cells." (PMID 35702951, 2022). "Crosslinking between CSCs and two pathways- TNF-α/ NF-κB signaling and IL-6/STAT3- regulates the differentiation of many immune cells in TME, promoting immunosurveillance and cancer progression." (PMID 36207500, 2022). "LLL12 is a known inhibitor of signal transducer and activator of transcription 3 (STAT3), which is constitutively active in various types of cancers." (PMID 36612248, 2022). "For instance, Rokavec and colleagues reported a feedback loop among IL-6, Stat3, and miR34a, which can increase the invasiveness of CRC cells while the overexpression of IL-8 induces cancer growth and metastatization." (PMID 35889921, 2022). "As an inflammatory cytokine from the cancer microenvironment, Interleukin-6 (IL-6) was reported to promote tumor progression via activating multiple signaling pathways, including JAK/STAT3, AKT/mTOR and Raf/MEK/ERK pathways." (PMID 35372504, 2022). "Apart from miR-382, STAT3 was also regulated by miR-1246, IL-6, IL-10, nuclear factor kappa-B p65, or ERK and promoted M2-type macrophages in the progression of carcinoma." (PMID 35585990, 2022). "In all the carcinoma and hematopoietic cancer networks, STAT1 and STAT3 interact with a similar panel of proteins, including MTOR, SRC and EGFR." (PMID 35229974, 2022). "Abnormal activation of epidermal growth factor receptor (EGFR) is common in different types of cancer including ESCC, which can upregulates the expression of PD-L1 through STAT3 signaling pathway." (PMID 34881181, 2021). "In several other cancers, HSP90 inhibitors allowed to discover other client proteins of HSP90, such as STAT3 or AKT11,52." (PMID 33737511, 2021). "PIPKI γ is highly expressed in the cancer tissues of CRC patients with poor prognosis, increases CCL2 expression through Akt-STAT3 signal activation, and recruits TAMs to the TME." (PMID 34445235, 2021). "STAT-3 regulates expression of SNAIL1/2 and leads to the so-called “cadherin switch” in cancer cells, independently of their chemoresistance." (PMID 33478150, 2021). "STAT3 accumulation was observed in specific sites, especially in basal and suprabasal layers of HPV16-positive early pre-cancer lesions, and STAT3 expression and activity were distinctively higher in poorly differentiated lesions." (PMID 33946372, 2021).
cancer (continued). "BRG1‐KO also sensitized GBM cells to the anti‐proliferative effects of the anti‐cancer agent temozolomide (TMZ), which is used to treat GBM patients in the clinic, and selectively altered STAT3 tyrosine phosphorylation and gene expression." (PMID 33528916, 2021). "In this study, we investigate how an intracellular signalling network (STAT1, STAT3, Bcl-2 and BAX) regulates important cellular states, either anti-apoptosis or apoptosis of cancer cells." (PMID 34631119, 2021). "Among the seven members of the STAT family, STAT3, particularly phosphorylated by JAK2, is one of the major players that has been detected in many cancers, including the brain, breast, ovarian, pancreatic, prostate, melanoma, squamous cell carcinoma, and lung." (PMID 33672756, 2021). "In ovarian cancer, STAT3 was found to promote FA uptake, driving activation of FABP4 that helped fuel cancer cell growth." (PMID 34766135, 2021). "Enrichment analysis of 50 cancer hallmarks and 132 immune signaling modules showed that CSF-1, MYC, TGF-β, JAK/STAT3, IFN-α, and the other 29 signaling pathways were enriched in C2 versus C1 subtype (P < 0.05)." (PMID 34722280, 2021). "Signal transducer and activator of transcription 3 (STAT3), is an important member of STATs family which has a major role in inflammation and human cancers." (PMID 35211395, 2021). "In this feedforward transcriptional cascade, insulin growth factor (IGF) signaling increases STAT3-inducing activation, which, in turn, favors NANOG/Slug activity, and promotes cancer cells stemness and EMT." (PMID 34440220, 2021). "STAT3, an important transcription factor constitutively activated in cancers, is bound specifically by GRIM-19 and this interaction inhibits STAT3-dependent gene expression." (PMID 34848745, 2021). "The phosphorylation levels of MEK1/2, ERK1/2, JAK2, STAT3, PI3K, and Akt in cancer cells were detected by western blot." (PMID 34642304, 2021). "Meanwhile, tipifarnib activity was found to reduce the phosphorylation of signal transducers and activators of transcription 3 (STAT3) and ERK, the latter of which is needed in exosome biogenesis, and both of which are needed for the growth of cancer cells." (PMID 33842540, 2021). "In cancer cells, activated AT1R subunits lead to activation of signaling cascades, including the JAK/STAT3, cSRC/FAK, PKC and JNK pathways, promoting migration and invasion." (PMID 34359936, 2021). "The molecule is known to induce a pro-tumorous microenvironment, angiogenesis, and metastasis, primarily via signaling through STAT3, making IL6 another attractive target for cancer therapy." (PMID 34064000, 2021). "As recent review reported several pathways in Treg from cancers including Foxp3, IRF4, PI3/AKT/FoxO axis, Helios, Eos, Nr4a, Bach2, E proteins and their inhibitor of DNA-binding (Id) counterparts, STAT3, and NF-kB." (PMID 34084175, 2021). "It is reported that high PDK4 expression indicates a worse prognosis of OC patients, and PDK4 activates the STAT3/AKT/NF-κB/IL-8 signal pathway to enhance the metastasis and glycolysis of OC cells, and to help cancer cells maintain stemness." (PMID 33926489, 2021). "Of interest, it has been previously demonstrated that the existence of crosstalk between PI3K and STAT3 signaling in human cancer PI3K transformed cells, where the pharmacological inhibition of PI3K prevented Tyr705 phosphorylation of STAT3." (PMID 34685616, 2021). "Meanwhile, matrine down-regulated the phosphorylation levels of MAPK/ERK, JAK2/STAT3, and PI3K/Akt signaling pathways by targeting Src in cancer cells." (PMID 34642304, 2021). "In summary, we found that many human cancer cell lines fail to respond to STING agonists, which can be rescued by JAK2/STAT3 inhibitors in some cases." (PMID 33790360, 2021). "Reports have shown that STAT3-negative regulators, such as SHP-1, SHP-2, SOCS1, SOOCS2, SOCS3, and PIAS1, can potentially prevent cancer progression." (PMID 34589421, 2021).
cancer (continued). "As already reported in many types of cancer, IL-6/JAK/STAT3 signaling is also significantly hyperactivated in the subset of ONB patients with a poor clinical prognosis." (PMID 34064009, 2021). "The development of cancer is strictly regulated by a variety of intracellular signaling pathways, such as AKT, mitogen-activated protein kinase (MAPK), and STAT3 pathways." (PMID 34527062, 2021). "STAT3 activation plays an important role in metastasis, and STAT3 increases the expressions of MMP2 and MMP9, which act as key mediators of the metastatic process of cancer cells." (PMID 34876128, 2021). "FGF/FGFR-dependent STAT3 activity has been correlated with resistance to doxorubicin, 5-fluorouracil, cisplatin, paclitaxel, and MEK/BRAF inhibitors in several cancers." (PMID 34830951, 2021). "The anti-cancer effects of sesamin have been attributed to its ability to reduce significantly the expression of NF-KΒ, IL6 and transcriptional target of STAT3." (PMID 33578642, 2021). "Enhanced cancer cell growth and migration are regulated by the activation of JAK2/STAT3 signaling and activated STAT3 further promotes circ-SOD2 expression through a positive feedback loop." (PMID 34205978, 2021). "It has been reported that SPNS2 generally showed a promoting effect in the genesis, apoptosis and migration of cancer, through S1P/S1PRs pathways activating downstream signaling such as AKT, STAT3, ERK, Ras and Rac." (PMID 34249729, 2021). "IL-6/STAT3 mediated miR-200c transformation and inhibited EMT process in breast and lung epithelial cancer cells." (PMID 34722553, 2021). "It has been reported that targeting STAT3 affected cell proliferation and migration in cancer cells, and activation of JAK/STAT3 signaling pathway via enhancing EMT increases tumorigenic and metastatic ability and chemoresistance in cancer cells." (PMID 34365903, 2021). "Niclosamide has been reported to interfere with multiple signaling pathways, including mTORC1, IL-6/JAK/STAT3, ERK, Src, and Wnt signaling in different lineages of cancer cells." (PMID 34272475, 2021). "Recent study showed that salidroside had anti-cancer effects and suppressed RCC proliferation through inhibition of JAK2/STAT3 signaling pathway." (PMID 33917914, 2021). "The database contains 10 common cancer types, 521 compounds, 131 pharmacological pathways, including PI3K/Akt, STAT3, PI3K/Akt/mTOR, Wnt/β-catenin and other signaling pathways." (PMID 34497528, 2021). "In this study, JAK/STAT3 pathway interfered with treatment response by regulating EMT, which confers on cancer cells a greater resistance to elimination by therapeutics." (PMID 34422809, 2021). "These exosomal miRNAs can directly induce signal transducer and activator of transcription 3 (STAT3) inhibition, promoting cancer progression and metastasis." (PMID 34616851, 2021). "Specifically, in cancer cells, IDO1 upregulation is mostly dependent on STAT1, and IL-27 regulation of PD-L1 occurs through signal transducer and activator of transcription 3 (STAT3)." (PMID 34944437, 2021). "In addition, STAT3 can be upregulated by Janus-activated kinase 2 (JAK 2), toll-like receptor 4 (TLR 4), human epidermal growth factor receptor (EGFR), IL-6-type family, and several G protein-coupled receptors (GPCRs), which significantly associates development of resistance in various cancers." (PMID 34577615, 2021). "Berberine modulates various signaling pathways, including PI3K/Akt, MAPKs, AMPK, STAT3, NF-κB, EGFR, ROS, and HIF-1α, to sensitize cancer cells to a broad spectrum of cancer therapies." (PMID 34576028, 2021). "In this report, we have investigated the impact of 3FC on STAT3 activation and subsequent signaling events in HCC cells and a preclinical orthotopic cancer model." (PMID 35053027, 2021).
cancer (continued). "Further exploration of the link between attachment-independent growth and STAT3/IDO1 activation (e.g., in the context of metastasis formation) would help to better define the biological relevance of this phenotype to cancer." (PMID 33831358, 2021). "Further, signal transducer and activator of transcription 3 (STAT3), FAK and Src are known to regulate cancer stem cell proliferation and self-renewal." (PMID 33726836, 2021). "Considering that LOXL3 is downregulated in some types of cancer, they supposed that the acetylation of the SH2 domain affected the role of STAT3 in the regulation of the cell cycle." (PMID 34440160, 2021). "Signal transducer and transcriptional activator (STAT) proteins, in particular STAT3 and STAT5, are continuously activated in many human cancers and are related to dysregulated cell proliferation and apoptosis." (PMID 33968766, 2021). "For many cancers, Th17-cell signatures (RORC, IL17, IL23, STAT3) are correlated with the worse clinical outcomes." (PMID 34781983, 2021). "Its inhibitory effect on the IL-6/STAT3 pathway also disappears after SOCS inactivation, resulting in continuous proliferation and invasion of cancer cells." (PMID 34976809, 2021). "Signal transducer and activator of transcription 3 (STAT3) is a vital member of the STAT protein families, and numerous studies have confirmed that STAT3 accelerates cancer cell proliferation and invasion and induces chemoresistance." (PMID 34025420, 2021). "The major oncogenic actions of TYK2 are mediated through STAT1, STAT3, and STAT5, and drugs targeting STATs are in development for cancer therapeutics." (PMID 34439323, 2021). "In KRAS-driven cancers, there is crosstalk between many signalling networks, including KRAS, PDGFR and MET, and many of these pathways are upstream of STAT3." (PMID 33658640, 2021). "STAT3 is the most widely reported OSM downstream signaling pathway, which is also considered to be an important node connecting inflammation and cancer." (PMID 34702277, 2021). "The Janus kinases (JAKs) are main activators of STAT3, and both JAK and STAT3 have been investigated as potential targets for cancer treatment." (PMID 33380422, 2021). "The presence of several STAT3, and a single HNF-1β TFBS in the NNMT promoter region suggest a mechanism for the observed induction of NNMT expression in cancer." (PMID 34680055, 2021). "Therefore, JAK2/STAT3 may be used as a potential target for cancer therapy." (PMID 34165442, 2021). "STAT3 can cooperate with other signalling nodules (mainly Src, SMAD and c-Myc) to mediate IL-6 and OSM promotion of EMP in cancer cells." (PMID 34361105, 2021). "Verteporfin-PDT induced EGFR and STAT3 expression in OVCAR-5 and H460 cancer cells, whereas the EGFR or STAT-3 silencing with siRNA augmented PDT efficacy." (PMID 34805140, 2021). "In the present study, we have investigated the STAT3 inhibitory efficacy of Tris DBA, a palladium-based compound, in HCC and MM cancer cells and preclinical cancer models." (PMID 34771643, 2021). "STAT3 has been shown to interact with ETC complex I and II, preserving their activity in mitochondria from mice hearts and enhance ATP production in human cancer cells." (PMID 34642818, 2021). "Sauchinone has been reported to inhibit the growth of cancer cells by inhibiting the activity of transcription factors such as HIF-1α and STAT3." (PMID 34643237, 2021). "The gene expression of many enzymes in glucose metabolism is regulated by the JAK/STAT3 pathway, and the role of PKM2/STAT3 pathway in cancer progression has attracted increasing attention." (PMID 34234853, 2021). "Matrine targeted Src, inhibited its kinase activity and tyrosine phosphorylation to inhibit the proliferation of cancer cells by down-regulating the downstream MAPK/ERK, JAK2/STAT3, and PI3K/Akt phosphorylation signaling pathways." (PMID 34642304, 2021). "Previous studies have shown that inhibition of STAT3 and HER2 reduces MDSCs and Treg activity and thus inhibits cancer progression." (PMID 34068008, 2021).
cancer (continued). "Upon deletion of DICER, several molecules and receptor tyrosine kinases, which are involved in IR and cancer development, were hyperphosphorylated (IGF1, IR, IRS-2, and STAT3)." (PMID 34199293, 2021). "Previous studies showed that activation of STAT3, ERK1/2, and PKC plays an important role in proliferation in cancer cells." (PMID 34381775, 2021). "The activation of STAT3 can increase the expression level of MRP1; therefore, MRP1 overexpression is often detected in various types of cancer." (PMID 34129726, 2021). "Alternatively, heteronemin inhibited activation of ERK1/2 and STAT3, but it increased PKCα phosphorylation in MCF-7 cancer cells." (PMID 34381775, 2021). "The results demonstrated that Src activator peptide increased and KX2-391 decreased the phosphorylation levels of MEK1/2, ERK1/2, JAK2, STAT3, PI3K, and Akt in cancer cells." (PMID 34642304, 2021). "STAT proteins including STAT‐3 and STAT‐5 are transcription factors involved in cancer cell proliferation and survival by regulating the transcription of cell cycle–related, survival‐related and apoptosis‐related genes." (PMID 34318593, 2021). "STAT3 and STAT5 proteins acting as potential oncogenes have often reported to be overexpressed in different cancers." (PMID 33807326, 2021). "Six signaling molecules known to be engaged in cellular senescence, that is, AKT, AP-1, ERK1/2, NF-κB, p38 MAPK, and STAT3, were tested using immunoblotting in young and DIPS cancer cells." (PMID 34674640, 2021). "Estrogen reversed the inhibitory effect of heteronemin against activation of ERK1/2 and STAT3 in MCF-7 cancer cells and activation of PKC and STAT3 in MDA-MB-231 cancer cells but diminished ERK1/2 in MDA-MB-231 cancer cells." (PMID 34381775, 2021). "Stemness is responsible for initiating metastasis and cancer recurrence, and miRNAs are involved in the maintenance of the cancer stem cell via targeting main signaling pathways such as WNT/β-catenin, NOTCH, NF-kB, PI3K/AKT/mTOR, BMI-1, and STAT3." (PMID 34846108, 2021). "Overall, advances in CAF classification and identification will be key to elucidating the full extent of CAFs in cancer biology and what CAF phenotypes are modulated by STAT3 activity." (PMID 34858425, 2021). "STAT3 is also involved by enhancing the acquisition of EMT and cancer stem cells traits by CRC cells, through transcriptional induction of NANOG TF." (PMID 34440220, 2021). "Many downstream signaling pathways of TRIM27 have been identified in cancer, including PTEN/AKT, p38, and STAT3." (PMID 34284744, 2021). "In regard to upstream events, we found that IL10 activates STAT3, which binds to the CCL16 promoter gene and enhances CCL16 expression, thereby increasing cancer cell stemness." (PMID 33500726, 2021). "Recent work has reported that niclosamide can disrupt multiple signaling pathways, including NFκB, STAT3, and WNT signaling, in a variety of cancer models and has broad clinical implications." (PMID 34260376, 2021). "The JAK-STAT signaling pathway is a key pathway for tumorigenesis, development, and immune escape, and STAT3 and STAT5 have attracted considerable attention in cancer biology." (PMID 34943817, 2021). "IL-6 enhances cancer cell migration and EMT by activating STAT3 and IL-11 to facilitate resistance to chemotherapeutic drugs." (PMID 34063828, 2021). "β-Caryophyllene, β -caryophyllene oxide, and α-humulene, have been also found to induce apoptotic cancer cell death through the regulation of different pathways, such as JAK1/STAT3, NF-kB and PI3K/AKT/mTOR/S6K1." (PMID 34771097, 2021). "Exosomes derived from BMSCs, which are components of the lung cancer microenvironment, mediate the transfer of miR-193a-3p, miR-210-3p, and miR-5100 and promote cancer cell invasion and EMT by activating STAT3 signalling." (PMID 34193120, 2021). "STAT3, a crucial member of STAT proteins, is one of the most prevailing oncogenes in human cancers, acting as a cancer booster in GC development." (PMID 34604066, 2021).